FAM174A (family with sequence similarity 174 member A)
Synonyms: NS5ATP6; TMEM157; UNQ1912; HGS_RE408
Tractability: Antibody: UniProt predicts a signal peptide or a membrane-spanning region.
Gene: Protein-coding gene on chromosome 5 (100,535,338 to 100,586,741, forward strand). Ensembl gene ENSG00000174132.
Subcellular location: Membrane
Subcellular location (Human Protein Atlas): Golgi apparatus; Cytosol
Gene Ontology:
Molecular function: protein binding
Cellular component: membrane
Genetic constraint (gnomAD): Loss-of-function variants: 9 observed, 8.33 expected, observed/expected ratio (o/e) 1.08, 90% interval 0.65 to 1.77. That is too few expected variants to judge how well the gene tolerates losing a copy. Missense variants: 200 observed, 203.84 expected, observed/expected ratio (o/e) 0.98, 90% interval 0.87 to 1.1. Synonymous variants: 94 observed, 95.7 expected, observed/expected ratio (o/e) 0.98, 90% interval 0.83 to 1.17.
Homologues: Orthologues: chimpanzee FAM174A (99% identical), macaque FAM174A (97% identical), pig FAM174A (85% identical), rabbit FAM174A (83% identical), guinea pig FAM174A (80% identical), dog FAM174A (76% identical), mouse Fam174a (68% identical), rat Fam174a (68% identical), tropical clawed frog fam174a (39% identical).
Diseases named in the same sentence as FAM174A in open-access papers:
FAM174A is named in the same sentence as 1 disease in open-access papers, as found by Europe PMC text mining. Sharing a sentence is not in itself a finding about the gene and the disease. The quoted sentences say what the papers report.
cancer (1 paper, 2023). A tumor composed of atypical neoplastic, often pleomorphic cells that invade other tissues. "The exact function of the other genes in the top rank, FAM174A, ARRDC2, and ARMS2, remained unknown in ATO or cancer research." (PMID 37251921, 2023).